CTLA4 (cytotoxic T-lymphocyte associated protein 4)
Diseases named in the same sentence as CTLA4 in open-access papers (continued):
Sharing a sentence is not in itself a finding about the gene and the disease.
lung cancer (continued). "The most commonly used immunotherapies for lung cancer block the interaction between PD1 and PDL1, and recent clinical trials suggested that anti-CTLA4 and anti-PD1 combination therapy improved the survival of patients independent of tumour PD1 expression." (PMID 38782901, 2024). "For advanced non‐small cell lung cancer (NSCLC), combination therapies including a PD‐1 inhibitor plus chemotherapy or a PD‐1 inhibitor, CTLA‐4 inhibitor, and chemotherapy are standard first‐line options." (PMID 38602166, 2024). "A flow cytometric analysis in lung cancer samples revealed that BTLA expressing tumor infiltrating CD8 positive T-cells also showed increased expression of the checkpoint receptors PD1, CTLA4, LAG-3 and TIM-3." (PMID 38928307, 2024). "Based on our own experience and the literature information on lung cancer, it is reasonable to propose that CIK cells (alone and also as DC/CIKs) should be preclinically assayed with PD-L1 and CTLA-4." (PMID 36982701, 2023). "A novel bsAB c-Met × CTLA-4 targeting c-Met and CTLA-4, a negative regulator of T cell activation, showed significant anti-tumor activity in lung cancer models in vitro and in vivo." (PMID 36900399, 2023). "This review article focuses on immune checkpoints inhibitors: CTLA-4 inhibitors (ipilimumab and tremelimumab) and PDL-1 inhibitors (durvalumab and atezolizumab) that can be blocked to treat lung carcinoma." (PMID 36237320, 2022). "BALB/c and C57BL/6 mice were subcutaneously inoculated with 1 × 106 cells of the lung cancer lines ASB-XIV or LLC1, respectively, and then received anti-PD-1, anti-CTLA-4, or a combination of both antibodies." (PMID 34771674, 2021). "Preclinical studies in lung cancer show that the EGFR pathway enhances immunosuppression through increased engagement of PD-1/PD-L1 and CTLA4 in an ERK and NFkB dependent manner." (PMID 33807608, 2021). "Here, we found that the PD-1 (PDCD1) and CTLA4 were only expressed in a sub-cluster of T cells in the peripheral blood, but the vast majority of TIL-T cells in lung cancer tissues expressed PD-1 and CTLA4." (PMID 35069521, 2021). "Perhaps most surprising to the field is that lung cancer can now be treated with PD-1 (CD279) and CTLA-4 (CD152) antagonists as a component of first line therapy." (PMID 32620755, 2020). "We found that CTLA4 was expressed in a subset of NSCLC cell lines and in a subgroup of cancer cells within the lung cancer tissues." (PMID 30378264, 2019). "In conclusion, we found important differences in PD-1 and CTLA-4 expression on CD8+ and CD4+ cells depending on the status of their activation in the lung cancer microenvironment." (PMID 31010080, 2019). "Recently we present elevated proportion of PD-1 and CTLA-4 positive cells and expression of these molecules on memory- activated CD8 cells in lung cancer milieu." (PMID 31867335, 2019). "We demonstrated that CTLA4 was expressed in a subset of NSCLC cell lines and in a subgroup of cancer cells within the lung cancer tissues." (PMID 30378264, 2019). "In the lung cancer tissue samples from NSCLC patients, CTLA4 and PD‐L1, are expressed not only in tumour‐infiltrated lymphocytes, but also lung cancer cells." (PMID 30378264, 2019). "Other observations that were of potential clinical relevance were that the brain metastasis of lung carcinoma expressed relatively high levels of MET, RON and CTLA-4." (PMID 31747973, 2019). "Similar results were seen in a recent report of patients with small cell lung cancer treated with PD-1 plus CTLA-4 blockade, suggesting the importance of TMB as biomarker for combination immunotherapy across lung cancers." (PMID 29657128, 2018).
lung cancer (continued). "They showed a higher percentage of CD8+ cells with (s)CTLA-4 and a higher percentage of CD4+ cells with (in)CTLA-4 in the lung cancer patients as compared to the healthy subjects." (PMID 27866241, 2017). "The aim of this study is to investigate the biological significance of heat shock protein gp96 and immune-related gene CTLA-4, CD8 expressions in lung cancer tissues of different progressive stages." (PMID 20704820, 2010). "JTX2011/vopratelimab is also being investigated in a phase I/II study of solid tumors in combination with either anti‐PD‐1 or anti‐CTLA‐4 therapy (NCT04319224) and in combination anti‐CTLA‐4 therapy in a phase 2 study of non‐small cell lung cancer and urothelial cancers (NCT03989362)." (PMID 41474629, 2026). "Based on studies lung cancer cells can stimulate abnormal CTLA-4 expression in T cells, so lung cancer cells might cooperate with the CTLA-4 pathway to escape from T cells." (PMID 38234663, 2024). "Using the Kaplan-Meier plotter database,we investigated the correlation between these factors and lung cancer patient survival, finding that PD-L1 and CTLA4 did not significantly affect OS." (PMID 39877375, 2024). "Cancers with high tumor-infiltrating lymphocytes (e.g., lung cancers) had high expression of immune-oncology markers, such as PD-L1, TIM3, FOXP3, PD-1, CTLA4, and LAG3 in TMA EdgeSeq and TCGA RNA-seq; this was also observed in normal hematopoietic tissues with TMA EdgeSeq." (PMID 36137139, 2022). "Thus, exploiting markers like CTLA-4, TIGIT, OX-40, 4-1BB and GITR, which we observed to be highly expressed by TIL-Tregs, can be a potential therapeutic target for the treatment of the lung cancer patients." (PMID 36566320, 2022). "In this context, PD-L1 and Cytotoxic T-lymphocyte protein 4 (CTLA-4) pathways, which are significantly involved in tumor-induced immune control, are now druggable and still under evaluation to elucidate gender differences also in lung cancer." (PMID 34769372, 2021). "Although immune checkpoint inhibitors appear promising for lung cancer treatment, not all lung cancer patients respond to immune checkpoint inhibitors against PD-1 and CTLA-4, possibly because of their complexity and limitations in their tumor immunity." (PMID 32346613, 2020). "With the advancement of lung cancer therapy, ICI therapy has become a first-line treatment regimen for non-operative locally advanced and metastatic NSCLC and SCLC, of which PD1 inhibitor (PD-1 antibody and PD-L1 antibody) is the most widely used, followed by CTLA-4 inhibitor." (PMID 36869304, 2023). "Such as in nonsmall cell lung cancer (NSCLC) as well as hepatocellular carcinoma (HCC), a malfunction CD8 + T cell population was discovered to be positively related to high levels of expression of suppressor receptor genes (PD1, PD-L1, LAG3, CTLA4, TIGIT, and HAVCR2)." (PMID 35845137, 2022). "In subcutaneous tumor models of diverse tumors, unlike the responses to PD-1, PD-L1 and CTLA-4 inhibitors or other cytokines, TRIM3 mRNA expression decreased specifically upon IFN-β stimulation in the LLC lung cancer model." (PMID 41545343, 2026). "At the same time, the expression of ADAMTS8 was not different between high and low levels of CTLA4 in lung cancer patients, and the benefits of higher ADAMTS8 expression were present regardless of the levels of CTLA4." (PMID 35743687, 2022). "Recent results from randomized Phase III trials in front‐line non‐small cell lung cancer (NSCLC) also suggest that high TMB may not be effective at predicting survival benefits from a combination of PD‐1 and CTLA4 inhibitors." (PMID 35124891, 2022).
non-small cell lung carcinoma (372 papers, 2013 to 2025). A group of at least three distinct histological types of lung cancer, including non-small cell squamous cell carcinoma, adenocarcinoma, and large cell carcinoma. "Another recently approved combinatorial therapy for the treatment of metastatic or advanced Non Small Cell Lung Cancer is the association of anti PDL-1 with anti CTLA-4." (PMID 38322766, 2024). "Immune checkpoint inhibitors (ICIs) targeting PD-1, cytotoxic T-lymphocyte-associated protein 4 (CTLA-4) and PD-L1 have been widely developed and have shown good efficacy in treating non-small cell lung cancer (NSCLC)." (PMID 37226190, 2023). "Blockade of cytotoxic T-lymphocyte–associated antigen 4 (CTLA-4) and programmed death 1 (PD-1) or the PD-1 ligand, PD-L1 have achieved survival rates of 30–50% in various cancers such as non-small cell lung carcinoma (NSCLC), melanoma, and bladder cancer." (PMID 36323740, 2022). "An elevated mutation burden has been associated with an increased rate of response to anti-CTLA-4 and PD-1 therapies, likely on account of a higher neoantigen burden leading to the antitumor immune response in non-small-cell lung cancer (NSCLC) and UVM." (PMID 35372330, 2022). "The expression of CTLA-4 on tumors has been linked with poor survival in nasopharyngeal carcinoma and increased survival in non-small cell lung cancer (NSCLC)." (PMID 32344837, 2020). "So far, the expression of CTLA-4 on tumors has been associated with decreased survival in nasopharyngeal carcinoma and increased survival in non-small cell lung cancer." (PMID 29644214, 2018). "Numerous clinical trials have confirmed that monoclonal antibodies targeting programmed cell death protein 1/programmed death ligand 1 (PD-1/PD-L1) and cytotoxic T lymphocyte-associated protein 4 (CTLA-4) can improve overall survival in patients with advanced non-small cell lung cancer (NSCLC)." (PMID 39995679, 2025). "Immune checkpoint therapy blocking PD-1, PD-L1, and/or CTLA-4 has proven to be successful in several cancer types, usually characterized by high mutation burdens and a relatively dense T-cell infiltrate, such as melanoma or non-small-cell lung cancer (NSCLC)." (PMID 35207374, 2022). "We assessed the relationship between imAE development and efficacy in metastatic non-small-cell lung cancer patients treated with durvalumab (anti-programmed cell death ligand-1 [PD-L1]) alone or in combination with tremelimumab (anti-cytotoxic T-lymphocyte-associated protein 4)." (PMID 36405729, 2022). "A recent study on non-small cell lung cancer (NSCLC) showed that increased cytotoxic T-lymphocyte-associated protein 4 (CTLA-4) in the tumor microenvironment could suppress the function of dendritic cells (DCs), resulting in immunosuppressive effects." (PMID 35368661, 2022). "The blockade of cytotoxic T-lymphocyte–associated antigen 4 (CTLA-4) and programmed death 1 (PD-1) or the PD-1 ligand, PD-L1 have achieved survival rates of 20–30% in treating cancers such as non-small cell lung carcinoma (NSCLC), melanoma, kidney, and bladder cancer." (PMID 34181666, 2021). "Immune checkpoint inhibitors (ICIs) targeting the programmed cell death (PD)-1 protein and its ligand, PD-L1, and cytotoxic T-lymphocyte-associated antigen (CTLA)-4, have revolutionized the management of patients with advanced non-small cell lung cancer (NSCLC)." (PMID 33918661, 2021). "Lastly, durvalumab (PD-L1 inhibitor) and tremelimumab (CTLA-4 inhibitor) are used for non-small cell lung cancer and hepatocellular carcinoma, enhancing the immune response by targeting different checkpoints." (PMID 40673965, 2025). "Immune checkpoint inhibitors (ICIs) targeting PD-1, PD-L1, and CTLA-4 have demonstrated significant efficacy in the treatment of non-small cell lung cancer (NSCLC)." (PMID 40988064, 2025).
non-small cell lung carcinoma (continued). "Immunotherapies targeting cytotoxic T lymphocyte antigen 4 (CTLA-4) and programmed cell death 1 (PD-1) have been used for the treatment of melanoma, non-small cell lung cancer (NSCLC), renal cell carcinoma (RCC), and Hodgkin's lymphoma 14-21." (PMID 40861815, 2025). "Published data from clinical trials with anti-CTLA-4 monoclonal antibodies or bispecific antibodies in non-small-cell lung cancer." (PMID 40075753, 2025). "The combination of PD-1/PD-L1 inhibitor with CTLA-4 inhibitor for advanced non-small cell lung cancer(NSCLC) is presently a significant area of research, however its clinical application remains contentious." (PMID 39981238, 2025). "Immune checkpoint inhibitors (ICIs) targeting programmed death-1 (PD-1), programmed death ligand 1 (PD-L1), and cytotoxic T lymphocyte antigen 4 (CTLA-4) have become one of the main therapeutic options for advanced non-small cell lung cancer (NSCLC)." (PMID 40612589, 2025). "Dual immune checkpoint blockade targeting PD-1 and CTLA-4 has revolutionized the management of metastatic melanoma and proved effective in other cancers, such as non-small cell lung cancer and renal cell carcinoma." (PMID 39856213, 2025). "As a first-line treatment option for advanced non-small cell lung cancer, the combination of a PD-1/PD-L1 inhibitor plus a CTLA-4 inhibitor is both effective and well tolerated." (PMID 39981238, 2025). "Common ICI combinations include nivolumab (PD-1 inhibitor) and ipilimumab (CTLA-4 inhibitor), used for melanoma, renal cell carcinoma, and non-small cell lung cancer." (PMID 40673965, 2025). "Therapies targeting the inhibitory checkpoints CTLA-4 and PD-1 axis induce prominent anti-tumor responses and lasting clinical benefit in patients with different tumor types, including non-small cell lung cancer (NSCLC)." (PMID 40091029, 2025). "In a study of patients with non-small cell lung cancer receiving PD-1 checkpoint blockade therapy, higher (vs. lower) expression of CTLA4 protein in the macrophage compartment assessed by the DSP assay was associated with worse survival." (PMID 39769193, 2024). "We succeeded in finding a single dataset meeting this criteria: a study of patients with non-small cell lung cancer who initially responded to ICB (anti-PD-1/PD-L1±anti-CTLA-4 Ab) but later developed resistance." (PMID 38378697, 2024). "Antibodies targeting the immune checkpoint molecules PD-1, PD-L1 and CTLA-4, administered alone or in combination with chemotherapy, are the standard of care in most patients with metastatic non-small-cell lung cancers." (PMID 38689060, 2024). "Nivolumab (PD-1 inhibitor) and ipilumumab (CTLA-4 inhibitor) are recently approved checkpoint inhibitors for treatment of non-small cell lung cancer." (PMID 38130914, 2023). "Immune checkpoint inhibitors (ICIs) in the form of anti-CTLA-4 and anti-PD-1/PD-L1 have become the frontier of cancer treatment and successfully prolonged the survival of patients with advanced non-small cell lung cancer (NSCLC)." (PMID 36845142, 2023). "A previous investigation discovered that PVR is a potential predictor or marker of anti-CTLA4 immune response in non-small cell lung cancer." (PMID 37266661, 2023). "As shown in CheckMate-227 for advanced non-small-cell lung cancer, dual blockade of PD-1 and CTLA-4 significantly improved OS compared with chemotherapy in both patients with TMB≥10 mut/Mb and those with TMB<10 mut/Mb via F1CDx." (PMID 37305681, 2023). "Being consistent with this, anti-PD-1/PD-L1/CTLA-4 treatments have demonstrated remarkable efficacy across various cancer types, encompassing non-small-cell lung cancer (NSCLC), melanoma, renal cell carcinoma, urologic cancer, and HCC." (PMID 37894413, 2023). "The combination of anti-PD-1/anti-PD-L1 and CTLA-4 inhibitors has shown enhanced activity in other tumour types like melanoma and non-small cell lung cancer (NSCLC)." (PMID 37686543, 2023).
non-small cell lung carcinoma (continued). "Immune checkpoint inhibitors (ICIs), such as programmed death-1 (PD-1), programmed death-ligand 1 (PD-L1), cytotoxic T lymphocyte antigen 4 (CTLA-4) antibodies, etc, have revolutionized cancer treatment strategies, including non-small cell lung cancer (NSCLC)." (PMID 36949956, 2023). "In short, T cells were isolated from blood samples taken from non-small-cell lung cancer patients prior and post-treatment with CTLA-4 blockade (ipilimumab) in combination with radiation therapy (RT)." (PMID 37002292, 2023). "The findings showed that this combined therapy in non-small cell lung cancer (NSCLC) is well tolerated when compared to CTLA4 with PD-L1 combined therapy, and that it improves responses and PFS in PD-L1–immune sensitive patients." (PMID 35656508, 2022). "In non-small cell lung cancer, analysis of CpG-methylation assays and bisulfite sequencing revealed that CTLA-4 and PD1 methylation levels were reduced compared to normal tissues and epigenetic changes were inversely correlated with gene expression." (PMID 35203421, 2022). "Targeting programmed cell death protein-1 (PD-1), programmed cell death ligand-1 (PD-L1), and cytotoxic T lymphocyte-associated protein-4 (CTLA-4) therapy has resulted in responses in various tumors such as Hodgkin’s lymphoma and non-small cell lung cancer." (PMID 33669885, 2021). "Anti-CTLA-4 and anti-PD-1/PD-L1 ICIs have been extremely successful for aggressive cancers such as advanced melanoma and non-small cell lung cancer (NSCLC), and there is growing interest in the utility of ICIs as a potential treatment for glioblastoma." (PMID 34054867, 2021). "The response to anti-CTLA4 treatments depends on Bacteroides species as shown both in mice and patients with melanoma and non-small cell lung cancer (NSCLC)." (PMID 34205397, 2021). "Immune checkpoint inhibitors (ICIs) targeting programmed cell death (ligand)-1 (PD-1/PD-L1) and/or cytotoxic T lymphocyte-antigen 4 (CTLA-4) have emerged as a promising treatment for patients with advanced non-small cell lung cancer (NSCLC)." (PMID 33927616, 2021). "Dual blockade of PD-1 and CTLA-4 with nivolumab and ipilimumab has been used to treat melanoma, renal cell carcinoma, and non-small-cell lung cancer in clinical trials." (PMID 34200219, 2021). "In summary, our in silico and experimental analyses suggest that non-small cell lung carcinoma will likely respond to a new generation of anti-CTLA-4 monoclonal antibodies." (PMID 31991588, 2020). "In patients with non-small cell lung cancer, the combined treatment anti-CTLA-4/anti-PD-1 was more efficient in patients with a higher TMB (≥10 mutations per megabase) compared to patients with a lower TMB." (PMID 32326073, 2020). "Surprisingly, non-small cell lung carcinoma (NSCLC) is predicted to be highly responsive to anti-CTLA-4 antibodies." (PMID 31991588, 2020). "The non-small cell lung carcinoma (NSCLC) was predicted to be highly responsive to anti-CTLA-4 antibodies." (PMID 33585561, 2020). "A recent retrospective study of two trials investigating either anti-PD1 or anti-CTLA4 agents given with SBRT for metastatic non-small cell lung cancer found that SBRT increased the efficacy of PD1 therapy by 98% relative to historical controls." (PMID 32850412, 2020). "Another preclinical study found an enhanced accumulation of the PET tracer, 64Cu-DOTA-ipilimumab in the CTLA4-expressing non-small cell lung cancer (NSCLC) tissues." (PMID 33298096, 2020). "Nonetheless, the favourable clinical responses seen in the current study can be compared with the disappointing historical studies of CTLA-4 inhibitors, both as single-agents and combined with chemotherapy, in metastatic non-small cell lung cancer." (PMID 30841910, 2019). "PD-1, PDL-1, and cytotoxic T lymphocyte antigen-4 (CTLA-4) are promising targets for the treatment of patients with breast and non-small cell lung cancer." (PMID 31620363, 2019).